RNU4-26P (RNA, U4 small nuclear 26, pseudogene)
Gene: Small nuclear RNA gene on chromosome 9 (20,418,321 to 20,418,427, forward strand). Ensembl gene ENSG00000222202.
Homologues: Orthologues: chimpanzee U4 (100% identical), macaque U4 (90% identical), dog U4 (66% identical), guinea pig U4 (65% identical), dog U4 (62% identical), rabbit U4 (59% identical). Paralogues in human: RNU4-4P (74% identical), RNU4-59P (68% identical), RNU4-67P (67% identical), RNU4-77P (67% identical), RNU4-34P (66% identical), U4 (66% identical), RNU4-53P (65% identical), RNU4-36P (64% identical), RNU4-13P (64% identical), RNU4-91P (64% identical), RNU4-86P (63% identical), RNU4-16P (62% identical), and 82 more.